HNRNPM (heterogeneous nuclear ribonucleoprotein M)
Diseases named in the same sentence as HNRNPM in open-access papers (continued):
Sharing a sentence is not in itself a finding about the gene and the disease.
cancer (continued). "The identification of AKAP8 in suppressing EMT and cancer metastasis was through a biochemical approach to capture proteins that interact with hnRNPM, previously shown to promote EMT and tumor metastasis by regulating alternative splicing of CD44." (PMID 31980632, 2020). "A total of 12 splicing factors were significantly associated with the OS of KIRC, among which splicing factors such as PCBP1, hnRNPK and hnRNPM were engaged in tumorigenesis through guiding alternative splicing programs in various cancers 31-33." (PMID 32047561, 2020). "We identified several cancer-associated splicing factors as G4 sensitisers, including SRSF10, HNRNPM and the known G4-interactor FUS, which is overexpressed in several cancers." (PMID 31287417, 2019). "Cancer stem cells marker ALDH1+ was found positively associated with overexpression of CD44s and hnRNPM." (PMID 31737791, 2019). "However, the role of HNRNPM in tumor progression appears to be cancer-type specific and highly context-dependent." (PMID 40784984, 2025). "Just as depletion of hnRNPC or hnRNPM leads to cell death due to sensing of endogenous dsRNAs arising from cryptic splicing, splicing inhibitors may reduce cancer viability through the same mechanism." (PMID 39221819, 2024). "Interestingly, hnRNPM has mostly been reported to drive tumor-promoting splicing programs in several cancer types." (PMID 39034402, 2024). "Among the top downregulated 50 genes, there were other cancer relevant genes such as cell cycle associated (CCNF1, CCNB1, ZWINT), cancer signaling (STK32B, IGF1, FLT1) and splicing associated (HNRNPM, HNRNPU, SRSF1) genes, which are active areas to investigate further." (PMID 38200580, 2024). "Besides different cancer hallmarks related to AS candidates, we also observed discrepant expression of HNRNPM SF transcripts in all three HCT116KO vs. WT." (PMID 35552415, 2022). "In addition, it also is necessary to examine tumor growth and cancer invasion and metastasis by the decreased expression of HNRNPM using the 3D culture and xenograft model." (PMID 33466816, 2021). "Therefore, this suggests that alterations in HNRNPM expression differ depending on the cancer site and that its effects also vary depending on the cancer type." (PMID 33466816, 2021). "Overall, our work offers mechanistic insight into the function of HNRNPM in prostate and other cancers, suggesting that HNRNPM could serve as a potential marker or drug target in cancer." (PMID 34075878, 2021). "HNRNPM regulates growth and splicing in other cancer cell lines." (PMID 34075878, 2021). "Understanding the extent to which mis-splicing of chromatin factors contributes to establishment of cancer, whether through HNRNPM or other splicing factors, will be important for future studies." (PMID 34075878, 2021). "Identification of other factors similar to HNRNPM that may similarly affect homeostasis of these genes can thus be important for cancer therapy." (PMID 34075878, 2021). "Taken together, our data reveal a role for HNRNPM in supporting cancer cell fitness." (PMID 34075878, 2021). "Several studies have previously implicated hnRNPM and SRSF3 in human cancers." (PMID 32023846, 2020). "Furthermore, among the 729 COSMIC cancer genes, the splicing of 22 genes was regulated by hnRNPM." (PMID 39034402, 2024). "If MAPK4 (TSS1500), HNRNPM, and PTGIR hypomethylation among smokers—what we observed—leads to greater protein expression, this could partially explain their increased risk for lung and heart diseases and several cancers." (PMID 35277542, 2022). "The hnRNPM contains three RNA recognition structural domains that regulate RNA alternative splicing and has recently been shown to induce EMT in cancer and contribute to the maintenance of the mesenchymal phenotype." (PMID 40746892, 2025). "Many of these new potential substrates, such as tubulin and hnRNPM, may help explain the growing list of MASTL functions including how MASTL promotes cancer, EMT and chemoresistance." (PMID 35732702, 2022).
cancer (continued). "The Heterogeneous nuclear ribonucleoprotein M (HNRNPM) binds to Rictor in the mTORC2 complex to enhance activation of AGC kinases, including SGK1, at least in muscle, but this protein is also involved in cancer invasion and metastasis." (PMID 29301334, 2018). "All in all, our results confirm that HNRNPM may play an important role in regulating growth across multiple, but not all, cancer types." (PMID 34075878, 2021). "Regardless, that PLANE links hnRNPM to repression of the NCOR2-202-generating AS is not in dispute since the process can be modelled in vitro and the action is sufficient to suppress cancer cell survival tumorigenicity." (PMID 34145290, 2021).
tumor (27 papers, 2012 to 2025). "The hnRNPM protein, a component of the spliceosome machinery, has been implicated in regulating tumor cell invasion, metastasis, and EMT progression." (PMID 40746892, 2025). "In vivo, HNRNPM knockdown significantly inhibited tumor growth in the presence of cisplatin, as demonstrated by representative tumor images, growth curves, and final tumor weights." (PMID 40476445, 2025). "Binds hnRNPM to suppress LUAD tumorigenicity; PARP4 deficiency causes splicing dysregulation → promotes tumor progression." (PMID 40904702, 2025). "The splicing regulator hnRNPM is a potentially novel PARP4 interaction partner, the loss of which likewise promotes tumor formation." (PMID 39034402, 2024). "The expression of this isoform has been proved to be controlled by hnRNPM during tumor metastasis, attesting the concept that splicing regulatory networks is a crucial mechanism for cancer phenotypes." (PMID 26273588, 2015). "Mechanistically, ubiquitously expressed hnRNPM can act in a mesenchymal-specific manner to precisely control CD44s splice isoform switching during the EMT observed in tumor metastasis." (PMID 26273588, 2015). "Additionally, LINC01089 plays a significant role in various tumor gene regulatory processes by acting as a modular scaffold, interacting with heterogeneous nuclear ribonucleoprotein M (hnRNPM), and influencing downstream molecular mediators." (PMID 39334363, 2024). "Additionally, other reports have shown that alternative splicing events modulated by hnRNPM were correlated with tumor progression." (PMID 37671887, 2023). "Interestingly, low expression of a cluster of HNRNPM-regulated circRNAs was significantly correlated with increased risk for patient biochemical relapse (BCR), and have a ‘tumor-suppressive’ function." (PMID 34075878, 2021). "Since most of the identified mRNAs that exhibited increased binding to hnRNPM were correlated with the KEGG term “Pathways in cancer,” AS1-S might affect the proliferation and expansion of BLV-infected cells and contribute to tumor progression." (PMID 37671887, 2023). "In our study, knockdown of HNRNPM in HCT116 xenograft models led to increased PSAT1 expression, yet had no observable impact on tumor growth." (PMID 40784984, 2025). "Four SFs were not significantly different between matched normal and tumor samples (CDC40, HNRNPH1, HNRNPCL1, and HNRNPM)." (PMID 37531400, 2023). "Importantly, down-regulation of HNRNPM /CEAR and not VEGF in endothelial cells suppresses tumor angiogenesis." (PMID 27583792, 2016). "Three proteins, caldesmon (CALD), heterogeneous nuclear ribonucleoprotein M (HNRNPM) and tropomyosin 1 (TPM1) were unique discriminative between LSCC and RSCC tumour cell-rich HND regions, however could not be identified as discriminative when the whole LSCC and RSCC tumour region were analysed." (PMID 40603632, 2024).
infection (11 papers, 2013 to 2025). The state of being infected such as from the introduction of a foreign agent such as serum, vaccine, antigenic substance or organism. "In contrast, PB2, PB1, PA, and NP proteins exhibited slight increases at 10 and 12 h post-infection, suggesting that hu-hnRNPM plays a critical role in differentially regulating the expression of the IAV genome." (PMID 40434105, 2025). "Next, we analyzed the role of hnRNPM after infection with L. monocytogenes, herpes simplex virus type 1 (HSV-1), and Sendai virus (SeV), which are known to be sensed by cGAS, STING, and/or RIG-I." (PMID 39707025, 2025). "It has been reported that hnRNPM shuttles from nucleus to cytoplasm after infection with SFV or CHIKV." (PMID 39707025, 2025). "Compellingly, hnRNPM KD significantly reduced ISRE reporter induction during infection with Listeria, HSV-1, or SeV." (PMID 39707025, 2025). "The growth titers of both strains were similarly reduced by more than 10-fold in hu-hnRNPM knockdown cells from 24 to 60 h post-infection, further supporting a role of hu-hnRNPM in the efficient replication of multiple IAV subtypes in human cells." (PMID 40434105, 2025). "Knockdown of hu-hnRNPM led to more than a 10-fold reduction in viral titers from 24 to 72 h post-infection, indicating its critical role in WSN virus replication." (PMID 40434105, 2025). "Similar to HNRNPM, RAI, LSM14A, LARP4, and CNOT2 showed complete loss of full-length protein during the course of infection." (PMID 38953667, 2024). "Following infection, hnRNPM was translocated from the nucleus to cytoplasm, which was impaired in RIG-I knockdown cells." (PMID 31433824, 2019). "Endogenous co-immunoprecipitation experiments indicated that hnRNPM interacted with RIG-I/MDA5 in a viral-infection-dependent manner." (PMID 31433824, 2019). "To investigate whether the role of ch-hnRNPM in IAV replication is similar to that of hu-hnRNPM in human cells, we examined the effect of ch-hnRNPM depletion on viral gene expression in a single round of infection in DF-1 cells." (PMID 40434105, 2025). "Interestingly, hnRNPM appeared preferly to bind to the 5’- terminus of SeV RNA and had a higher affinity with viral RNA in the late phase of infection." (PMID 31433824, 2019). "Notably, the increased mRNA levels of the PB2 segment observed in hu-hnRNPM knockdown cells at later stages of a single-cycle infection may result from the slow accumulation of NS1/NS2 proteins." (PMID 40434105, 2025). "However, SeV or EMCV infection resulted export of hnRNPM from the nucleus to cytoplasm." (PMID 31433824, 2019). "Specifically, hu-hnRNPM knockdown slightly increased PB2 mRNA levels at 8 and 10 h post-infection, while significantly decreasing NA mRNA levels at all time points." (PMID 40434105, 2025). "To investigate the role of hnRNPM in IAV replication, we performed siRNA-knockdown experiments in A549 cells, followed by infection with the WSN virus." (PMID 40434105, 2025). "Moreover, hu-hnRNPM knockdown decreased IRF3 protein levels at 0, 4, and 8 h post-infection and reduced the phosphorylation of IRF3 induced by IAV infection at 8 and 12 h." (PMID 40434105, 2025). "To further investigate, we assessed viral RNA levels at 6 h post-infection and observed that depletion of ch-hnRNPM did not affect the mRNA levels of the eight viral segments." (PMID 40434105, 2025). "Hypothetically, since BLV expresses few viral antigens during the latent phase of infection, suppression of immune responses might not be required in latently infected cells, and the interaction of AS1-S and hnRNPM could have another role other than immune suppression." (PMID 37671887, 2023).
HNRNPM also shares sentences with these, for which no sentence is quoted: hepatocellular carcinoma (4 papers); ovarian carcinoma (3); lymphoma (2); Alzheimer disease (1); amyotrophic lateral sclerosis (1); cervical cancer (1); cutaneous squamous cell carcinoma (1); Dengue virus infection (1); Fanconi anemia (1); heart diseases (1); leukemia (1); lymph node metastases (1); myopathy (1); neurodegenerative disease (1); Obesity (1); osteoarthritis (1); pancreatic adenocarcinoma (1); prostate adenocarcinoma (1); psoriasis (1); renal carcinoma (1); thyroid cancer (1).